RNU2-14P (RNA, U2 small nuclear 14, pseudogene)
Gene: Small nuclear RNA gene on chromosome 14 (65,124,352 to 65,124,542, reverse strand). Ensembl gene ENSG00000222985.
Homologues: Orthologues: chimpanzee U2 (99% identical), macaque U2 (90% identical), dog U2 (79% identical), rat LOC120093443 (75% identical), guinea pig U2 (73% identical), mouse Gm26256 (71% identical), rabbit U2 (46% identical). Paralogues in human: RNU2-64P (85% identical), RNU2-2 (85% identical), RNU2-36P (85% identical), RNU2-23P (84% identical), U2 (84% identical), RNU2-61P (83% identical), RNU2-3P (83% identical), RNU2-48P (83% identical), RNU2-59P (82% identical), RNU2-26P (81% identical), RNU2-32P (81% identical), RNU2-43P (81% identical), and 66 more.